Y_RNA (Y RNA )
Gene: Miscellaneous RNA gene on chromosome 1 (184,315,658 to 184,315,765, forward strand). Ensembl gene ENSG00000207080.
Homologues: Orthologues: chimpanzee Y_RNA (99% identical), macaque Y_RNA (94% identical). Paralogues in human: Y_RNA (87% identical), RNY1P5 (86% identical), Y_RNA (84% identical), Y_RNA (83% identical), Y_RNA (82% identical), Y_RNA (81% identical), RNY1 (80% identical), RNY1P1 (80% identical), Y_RNA (80% identical), Y_RNA (79% identical), Y_RNA (78% identical), RNY1P6 (77% identical), and 94 more.